KCNK2 (potassium two pore domain channel subfamily K member 2)
Diseases named in the same sentence as KCNK2 in open-access papers:
KCNK2 is named in the same sentence as 106 diseases in open-access papers, as found by Europe PMC text mining. Sharing a sentence is not in itself a finding about the gene and the disease. The quoted sentences say what the papers report.
depression (42 papers, 2010 to 2025). "KCNK2 is highly expressed in the central nervous system (CNS) and as such has been linked to a variety of neuropatholgies such as depression, pain and stroke." (PMID 30333618, 2018). "This molecule has been shown to display a therapeutic effect in mouse models of depression, a feature linked to its specific inhibition KCNK2." (PMID 30333618, 2018). "The KCNK2 gene encodes a K+ channel and has been associated with adrenal aldosterone-producing adenomas, hereditary hypertension, and depressive disorders." (PMID 28002425, 2016). "For KCNK2 gene that encodes for a two-pore-domain background potassium channel, a recent genetic study revealed its association with susceptibility of major depressive disorder and response to antidepressant treatment." (PMID 23264780, 2012). "Indeed, assays have been developed which cover a wide range of conditions associated with KCNK2, ranging from depression and nociception to cardiac form and function." (PMID 30333618, 2018). "A study examined SNPs in the KCNK2 gene in 565 patients with major depression and found that variations in SNPs (rs12136349, rs2841616, rs2841608) correlated with the response to citalopram treatment." (PMID 39529121, 2024). "KCNK2 channels are expected to become an interactive target for the treatment of depression, cerebral ischemia, general anesthesia, analgesics, ventricular tachycardia, and cancer." (PMID 38410243, 2024). "Until now, TREK-1 has been viewed as a novel antidepressant target, because TREK-1 activity is inhibited by antidepressants and the deletion of TREK-1 (KCNK2−/−) resulted in antidepressant-like behavior in models of depression." (PMID 29156592, 2017). "We recently identified a conserved mouse potassium channel protein called TREK-1 (KCNK2) as a new target for treating depression." (PMID 20405001, 2010). "In the field of depression and anxiety-related disorders, the background potassium channel TREK-1 (Twik related potassium channel 1) has been one of the first targets for which deletion of its gene (Kcnk2−/−) in mice resulted in a depression-resistant phenotype highlighted by behavioral tests." (PMID 30127743, 2018). "Indeed, Kcnk2 knockout mice show a resistance to depression due to enhanced 5-hydroxytryptamine (serotonin) neurotransmission and an increase in neurogenesis." (PMID 30333618, 2018).
ischemia (20 papers, 2011 to 2025). A hypoperfusion of the BLOOD through an organ or tissue caused by a PATHOLOGIC CONSTRICTION or obstruction of its BLOOD VESSELS, or an absence of BLOOD CIRCULATION. "Third, in rat hippocampal astrocytes, the increase of KCNK2 expression mediates neuroprotection during ischemia." (PMID 30519892, 2019). "This particular property suggests a putative protective role for KCNK2 against ischemia and pain, in which disrupted metabolism promotes intracellular acidification." (PMID 30333618, 2018).
Cerebral ischemia (13 papers, 2010 to 2025). Restriction of arterial blood supply to the brain associated with insufficient oxygenation to support the metabolic requirements of the tissue. "KCNK2, also known as TREK-1, has been reported to participate in cerebral ischemia and express widely in the brain." (PMID 41170376, 2025). "To summarize, KCNK2 controls several major cellular responses involved in memory formation and is believed to participate in neuroinflammation, cerebral ischemia and blood–brain barrier dysfunction." (PMID 30519892, 2019).
prostate carcinoma (8 papers, 2013 to 2023). A carcinoma that arises from epithelial cells of the prostate gland. "The TWIK-related potassium channel (TREK–1, also known as KCNK2) is a K2P channel that is highly expressed in cardiac, lung, and other tissues; it worsens various tumors, such as ovarian cancer and prostate cancer, and mediates cardiac fibrosis." (PMID 37238950, 2023).
cardiac arrhythmia (7 papers, 2017 to 2026). Any disturbances of the normal rhythmic beating of the heart or MYOCARDIAL CONTRACTION. "In this respect, KCNK2 plays an important role in neuroprotection and has also been linked to cardiac arrhythmias." (PMID 30333618, 2018).
Anxiety (6 papers, 2010 to 2023). Intense feelings of nervousness, tension, or panic often arise in response to interpersonal stresses. "This indicates that Kcnk2 mediates phenotypes like anxiety (light/dark avoidance) and coordination (Rota-rod) that did show up in RCS-IX." (PMID 23308133, 2013).
Sinus bradycardia (5 papers, 2016 to 2022). Bradycardia related to a mean resting sinus rate of less than 50 beats per minute. "The cardiac-specific knockout of Kcnk2, which encodes TREK-1, produces a stress-induced sinus bradycardia with a phenotypical manifestation that largely resembles the one described for Popdc1 and Popdc2 null mutants." (PMID 34940515, 2021). "A cardiac specific knockout of Kcnk2, which encodes TREK-1, displays a stress-induced sinus bradycardia similar to the one observed in Popdc1 and Popdc2 null mutants, suggesting that the sinus bradycardia in POPDC mutants may in part be due to an impaired TREK-1 current." (PMID 28939104, 2017).
breast cancer (4 papers, 2022 to 2025). A primary or metastatic malignant neoplasm involving the breast. "Furthermore, KCNK2 has been evaluated as a prognostic factor in various tumors, and high expression in breast cancer has been associated with improved overall survival rates." (PMID 41168812, 2025). "High expression of KCNK1 and KCNK2 was associated with increasing macrophage in breast cancer." (PMID 35656548, 2022). "The expression of KCNK1/4/6/9/10/13 were significantly upregulated, while KCNK2/3/5/7/17 were downregulated in breast cancer tissues compared to normal mammary tissues." (PMID 35656548, 2022). "High expression of KCNK2 and KCNK13 levels were associated with favorable disease-free survival in patients with breast cancer." (PMID 35656548, 2022). "The study also identified 22 unique ion channels in the metastatic state, of which GRIK2, GJB3, KCNB2, KCNA1 and KCNK2 were previously reported in breast cancer metastasis." (PMID 35326596, 2022). "Increased expression of KCNK1/3/4/9 was correlated with poor overall survival, while high expression of KCNK2/7/17 predicted better overall survival in breast cancer." (PMID 35656548, 2022). "In addition, we found that breast cancer patients with metastasis disease have low expression of KCNK2 and KCNK13." (PMID 35656548, 2022). "KCNK2 was detected as a prognostic factor in breast cancer, which was similar with previous study." (PMID 35656548, 2022). "Additionally, KCNK2/3/5/7/17 were significantly downregulated in breast cancer samples." (PMID 35656548, 2022). "KCNK2 is known to be highly expressed in the central nervous system, and various studies have performed on the role of KCNK genes in breast cancer treatment and prevention strategies." (PMID 41168812, 2025). "The RNA expression level of KCNK2, KCNK5, KCNK9, KCNK13, and KCNK15 were validated in human breast cancer cell lines." (PMID 35656548, 2022). "We found that KCNK2 and KCNK5 was downregulated in breast cancer, while KCNK9, KCNK13, and KCNK15 was upregulated in breast cancer." (PMID 35656548, 2022). "Our results revealed that KCNK9, KCNK13, and KCNK15 was significantly upregulated in breast cancer cell lines including MDA-MB-231 and SK-BR-3 cell lines, while KCNK2 and KCNK5 was downregulated in breast cancer cell lines comparing with breast epithelial cell line MCF-10A." (PMID 35656548, 2022).
ovarian carcinoma (4 papers, 2015 to 2023). A malignant neoplasm originating from the surface ovarian epithelium. "For example, KCNK2/10 were overexpressed in ovarian cancer, and KCNK2 regulators played an important role in cell proliferation and apoptosis." (PMID 35656548, 2022).
Brain atrophy (3 papers, 2019 to 2025). Partial or complete wasting (loss) of brain tissue that was once present. "Kcnk2 is a two-pore domain background K+ channel that can also mark brain atrophy per cognitive impairment and AD." (PMID 40979532, 2025). "Because sulcal widening is a marker of cortical atrophy as we pinpointed in the previous paragraph, there is a potential link between KCNK2 expression level and brain atrophy." (PMID 30519892, 2019).
experimental autoimmune encephalomyelitis (3 papers, 2012 to 2025). An autoimmune demyelinating disease of the central nervous system that is produced experimentally in animals by the injection of homogenized brain or spinal cord in Freund's adjuvant. "Interestingly, in experimental autoimmune encephalomyelitis (EAE), an animal model for multiple sclerosis (MS), K2P2.1-deficient mice (Kcnk2−/−) developed a worsened disease course with increased CNS immune cell infiltration compared to wild-type (WT) mice." (PMID 40681505, 2025).
memory impairment (3 papers, 2019 to 2023). "Finally, KCNK2 over expression was shown to exacerbate memory impairment in middle-age mice." (PMID 30519892, 2019).
liver cancer (2 papers, 2019 to 2021). An epithelial or non-epithelial malignant neoplasm that arises from the liver. "We observed reduced expression of KCNK2, KCNK15, and KCNK17 in liver cancer, as well as overexpression of KCNK9, all of which correlated with a better prognosis for HCC patients per survival analyses." (PMID 31581133, 2019).
autism (1 paper, 2016). Persistent deficits in social interaction and communication and interaction as well as a markedly restricted repertoire of activity and interest as well as repetitive patterns of behavior. "Reduced amount of KCNK2 protein may thus contribute to the failure or delay in neuronal migration that has been observed in some cases of autism and ID." (PMID 26753090, 2016).
diabetes (1 paper, 2012). "For example, high expression of Pla2g5 and/or Prl5a1, as well as low expression of Ankrd2 and/or Pappa2, indicates exposure to diabetes, while low expression of Kcnk2 and/or Mmp13 indicates exposure to breeder diet." (PMID 22701643, 2012).
encephalomyelitis (1 paper, 2020). Inflammation of the brain and the spinal cord. "Kcnk2 has the potential to reduce encephalomyelitis scores and lymphocyte infiltration into the central nervous system, indicating that drugs targeting the regulation of Kcnk2 activity may be used to treat various BBB injury-related neurological diseases." (PMID 31959866, 2020).
hypothyroidism (1 paper, 2018). Abnormally low levels of thyroid hormone. "As examples, microarray analysis revealed that hypothyroidism induces significant reductions in KCNK2 transcripts." (PMID 29351231, 2018).
keratoconus (1 paper, 2025). A degenerative, structural disorder of the eye, characterized by a cone-shaped protrusion of the cornea. "The potassium channel KCNK2 was found to be down-regulated with log2FC −3.633864363 indicating that deregulation of this ion channel might have high probability of contributing to increased cortisol levels in patients with progressive keratoconus." (PMID 39420106, 2025).
pancreatic ductal adenocarcinoma (1 paper, 2022). An infiltrating adenocarcinoma that arises from the epithelial cells of the pancreas. "TREK-1(KCNK2) may be a promising novel target for pancreatic ductal adenocarcinoma." (PMID 35656548, 2022).
thyroid cancer (1 paper, 2020). "Survival analysis using the Kaplan-Meier Plotter database revealed that KCNK2/3/4/5/12/15 were associated with overall survival (OS) in patients with thyroid cancer." (PMID 32742463, 2020). "Additionally, ROC curves were conducted to evaluate the diagnostic effect of KCNK2/4/5/15 in thyroid carcinoma." (PMID 32742463, 2020). "Next, the genes related to KCNK2/4/5/15 and differentially expressed in thyroid cancer were collected by LinkedOmics to investigate the mechanism of KCNK2/4/5/15 in thyroid cancer." (PMID 32742463, 2020). "Then, we used the TIMER database to explore the relationship between KCNK2 /4/5/15 expression and infiltrating immune cells in thyroid cancer." (PMID 32742463, 2020). "To further discover the targets of KCNK2/4/5/15 in thyroid carcinoma, we analyzed the possible kinase, miRNA and transcription factor target using LinkedOmics database." (PMID 32742463, 2020). "This study implied that KCNK2, KCNK4, KCNK5 and KCNK15 are potential targets of precision therapy for patients with thyroid cancer and these genes are new biomarkers for the therapeutic target for thyroid cancer." (PMID 32742463, 2020). "Interestingly, the results that the low mRNA levels of KCNK2 and KCNK3 were related to longer overall survival in thyroid cancer patients was inconsistent with different analyses of the UALCAN database, which showed low KCNK2 and KCNK3 expression in thyroid cancer." (PMID 32742463, 2020). "In summary, by analyzing the differential expression of KCNKs genes, clinical staging analysis, prognosis analysis and functional enrichment analysis, we found that only four genes, KCNK2, KCNK4, KCNK5, and KCNK15, may play a role in the carcinogenesis of thyroid cancer." (PMID 32742463, 2020).
cancer (9 papers, 2013 to 2024). A tumor composed of atypical neoplastic, often pleomorphic cells that invade other tissues. "The data show that mRNA expression of KCNK1, KCNK7, and KCNK9 is upregulated in cancer tissues while KCNK2, KCNK3, KCNK5, KCNK10, KCNK13, KCNK15, and KCNK17 levels are decreased compared to controls." (PMID 31581133, 2019). "KCNK2 is overexpressed in prostate and epithelial ovarian cancer, among other cancer types." (PMID 31581133, 2019). "Therefore, membrane hyperpolarization due to the up-regulation of KCNK1/KCNK2 channel expression facilitates Ca2+ influx through ROC and SOC channels in IPAH-PASMCs, similar to that in non-excitable cells, such as epithelial, endothelial, immune, and cancer cells." (PMID 38410243, 2024).
tumor (6 papers, 2015 to 2026). "Compared with tumor-adjacent tissues, KCNK5 and KCNK15 proteins were higher in PTC tissues and KCNK2 and KCNK4 proteins were lower in PTC, especially in PTC cytoplasm." (PMID 32742463, 2020). "To confirm our conclusions above, we used qRT-PCR to measure the mRNA levels of KCNK2, KCNK9, KCNK15, and KCNK17 in 90 pairs of HCC specimens and matched non-tumor specimens, which were surgically removed from HCC patients." (PMID 31581133, 2019). "Next, we used Western Blot to measure the protein levels of KCNK2, KCNK9, KCNK15, and KCNK17 in four pairs of HCC tissues and matched non-tumor tissues." (PMID 31581133, 2019). "Finally, we assessed the expression of KCNK2/4/5/15 in PTC and matched tumor-adjacent tissues by immunohistochemical staining of the PTC tissue microarray with 58 patient cases." (PMID 32742463, 2020). "Moreover, a total of 7 KCNKs were found to be closely related to the tumor stage, which were KCNK1, KCNK2, KCNK5, KCNK6, KCNK7, KCNK19, and KCNK15." (PMID 32742463, 2020). "We did not observe differential expression of KCNK1, KCNK2, or KCNK5 for different tumor grades." (PMID 31581133, 2019).
mental illness (1 paper, 2017). "Different genetic variants of the two-pore domain potassium channel TREK-1 (encoded by the KCNK2 gene), which contributes to setting the resting membrane potential, are linked to mental illness." (PMID 28089656, 2017).
KCNK2 also shares sentences with these, for which no sentence is quoted: migraine (16 papers); epilepsy (9); atrial fibrillation (7); neurological diseases (6); cardiac hypertrophy (5); Stroke (5); Arrhythmia (4); heart failure (4); mood disorder (4); allergic rhinitis (3); amyotrophic lateral sclerosis (3); heart diseases (3); pulmonary arterial hypertension (3); schizophrenia (3); bipolar disorder (2); cardiovascular disease (2); central nervous system diseases (2); cognitive disorder (2); colon inflammation (2); endothelial dysfunction (2); fibrosis (2); irritable bowel syndrome (2); lung carcinoma (2); multiple sclerosis (2); sick sinus syndrome (2); ventricular tachycardia (2); acute lung injury (1); acute myocardial infarction (1); adenomyosis (1); atrioventricular block (1).
A further 53 diseases each share a sentence with KCNK2 in 1 paper.